NOX4 (NADPH oxidase 4)
Diseases named in the same sentence as NOX4 in open-access papers (continued):
Sharing a sentence is not in itself a finding about the gene and the disease.
glioblastoma (29 papers, 2011 to 2026). The most malignant astrocytic tumor (WHO grade IV). "Stable NOX4 knockdown by shRNA significantly reduces ROS production and suppresses glioblastoma cells proliferation and invasion and tumor-associated angiogenesis." (PMID 28594389, 2017). "Nox4 knockdown reduced ROS production significantly and suppressed glioblastoma cells proliferation and invasion and tumor associated angiogenesis and increased their radiosensitivity in vitro." (PMID 24868315, 2014). "In conclusion, our findings indicate that Nox4 is associated with tumor invasion, angiogenesis, and radioresistance in glioblastoma." (PMID 24868315, 2014). "Nevertheless, the comprehensive mechanisms underlying the elevated levels of NOX4-derived ROS in aerobic glycolysis and downstream target genes in glioblastoma cells remain largely unknown." (PMID 34740322, 2021). "Glioblastoma cells demonstrate a distinct ROS profile characterized by elevated NADPH oxidase 4 (Nox4) expression, which drives both tumor invasion and angiogenesis, setting them apart from other solid tumors where different ROS-generating systems predominate." (PMID 41009025, 2025). "For example, the NOX4 gene has the greatest influence on classification, and its expression levels are more critical for predicting astrocytomas and glioblastomas than oligodendrogliomas." (PMID 40867242, 2025). "Co-culturing these NOX4-knockdown HUVECs with U251 glioblastoma cells resulted in decreased proliferation of cancer cells." (PMID 38985083, 2024). "NOX4-derived ROS arbitrates TGF-β1-induced metabolic reprogramming during EMT via PI3K/AKT/HIF-1α pathway in glioblastoma." (PMID 38720270, 2024). "In thyroid carcinoma, NOX4 induced glycolysis by shifting oxidative phosphorylation to glycolysis Another study showed that NOX4 deletion suppresses the aerobic respiration in glioblastoma." (PMID 37044213, 2023). "In glioblastoma, the aberrant NOX4-dependent ROS generation affects the regulation of FOXM1 by mediating HIF1α stabilization." (PMID 36768405, 2023). "The expression of NFE2L2 increases with the histological severity of glioma, and NOX4 is also significantly increased in the gradeIV glioblastoma." (PMID 36627482, 2023). "TGF-β1 mediates NOX4 upregulation that, in turn, promotes ROS generation, growth, survival, hypoxia, and the angiogenesis of glioblastoma." (PMID 36768405, 2023). "We analyzed the correlation between angiogenesis and the NOX4 expression in glioblastoma and then performed immunofluorescent co-staining against CD31." (PMID 36278207, 2022). "This was the first study to demonstrate that TSPO was the upstream target of NOX4-derived mitochondrial ROS, necessary for NOX4-derived mitochondrial ROS-induced angiogenesis in glioblastoma." (PMID 36278207, 2022). "However, mechanisms underlying Nox4-derived ROS levels in glioblastoma are largely unknown." (PMID 36278207, 2022). "Our data revealed that the TGFβ pathway regulates these functions via NOX4‐derived ROS, as well as demonstrating that NOX4 alone is a key regulator of stemness in glioblastoma." (PMID 35203105, 2022). "Tulipic acid induces ferroptosis in glioblastoma cells by activating NADPH oxidases 4 (NOX4) and inhibiting system Xc−." (PMID 36506514, 2022). "The aim of this study was to elucidate the detailed mechanism of the role of NOX4 in angiogenesis in glioblastoma." (PMID 36278207, 2022). "Cycling hypoxic glioblastoma cells exhibit significantly upregulated NOX4 expression and ROS production compared with normoxic cells." (PMID 35646942, 2022). "RNA sequencing data from The Cancer Genome Atlas (TCGA) Glioblastoma dataset showed that the mRNA expression of NOX4 was enriched in glioblastoma compared to low-grade glioma and non-tumor tissues." (PMID 36278207, 2022). "Clinical samples of glioblastoma showed NOX4 expression in CD31-positive endothelial cells attached to the newly forming vasculature within the tumor region." (PMID 36278207, 2022).
glioblastoma (continued). "The aim of this study was to perform a complete mechanistic analysis of NOX4-mediated TSPO-induced ROS elevation in angiogenesis in glioblastoma." (PMID 36278207, 2022). "Further, the Chinese Glioma Genome Atlas (CGGA) and TCGA Low-Grade Glioma datasets showed that NOX4 expression was significantly higher in glioblastoma comparing with other histological types." (PMID 36278207, 2022). "We demonstrated for the first time that FOXM1 contributed to aerobic glycolysis in glioblastoma and that this effect was regulated by NOX4-derived MitoROS generation, extending the role of FOXM1 as a master regulator of cancer metabolism." (PMID 34740322, 2021). "Collectively, from both gain-of-function and loss-of-function studies, our data suggest that both NOX4 and FOXM1 play essential roles in regulating aerobic glycolysis and proliferation in glioblastoma cells." (PMID 34740322, 2021). "In summary, we identified for the first time that FOXM1 is a novel downstream target of NOX4-derived MitoROS, which is required for NOX4-derived MitoROS-induced aerobic glycolysis and progression in glioblastoma." (PMID 34740322, 2021). "In the present study, we found that FOXM1 and NOX4 were overexpressed in glioblastoma and established these factors as strong biomarkers for diagnosis and prognosis." (PMID 34740322, 2021). "In glioblastoma, NOX4 is the most frequent NOX isoform, and aberrant ROS generation of NOX4 contributes to cell proliferation and survival." (PMID 34740322, 2021). "Nox4 is a key factor involved in the regulation of ROS production and is upregulated in glioblastoma compared with other nicotinamide adenine dinucleotide phosphate: NADPH oxidase isoforms." (PMID 32962073, 2020). "Like other NOX enzymes, NOX4 also plays a pro-cancer role, and it is up-regulation has been reported in renal cell carcinoma, melanoma, glioblastoma multiforme (GBM), ovarian, and pancreatic cancer." (PMID 31288436, 2019). "The NADPH oxidase 4 (Nox‐4)/ROS/Akt signaling is known to regulate survival, proliferation infiltration and invasion in glioblastomas (GBMs)." (PMID 29460395, 2018). "Taken together, NOX4 is implicated in tumor angiogenesis of different cancer types, including fibrosarcoma, VHL-deficient RCC, glioblastoma and human astroglioma." (PMID 28594389, 2017). "The NOX4-mediated ROS are known to contribute to cycling hypoxia-promoted tumor progression with activation of HIF-1α in glioblastoma cells and xenografts." (PMID 27043542, 2016). "Knockdown of Nox4 expression reduced ROS production significantly and suppressed glioblastoma cell proliferation and invasion and tumor induced angiogenesis as well as increased their radiosensitivity." (PMID 24868315, 2014). "Accordingly, inhibition of Nox4 using lentivirus-mediated Nox4 shRNA suppressed glioblastoma cell proliferation and clonogenic survival following radiation." (PMID 24868315, 2014). "In glioblastoma, the expression levels of Nox4 mRNA were significantly higher than those in other astrocytomas (WHO grades II and III)." (PMID 24868315, 2014). "Our study demonstrates that Nox4 was involved in ROS generation and Nox4 knockdown inhibited cell invasion, angiogenesis, and promoted radiation response in human glioblastoma." (PMID 24868315, 2014). "The Nox4 immunohistochemical analysis in GBM8401-Luc xenografts demonstrated that Dox induction of shRNAs targeting Nox4 in vivo also led to suppression of Nox4 expression in glioblastoma tumors." (PMID 21935366, 2011). "Nox4 knockdown or Tempol treatment in vivo suppresses cycling hypoxia-induced ROS levels in glioblastoma." (PMID 21935366, 2011). "In this study, both TSPO and NOX4 promoted angiogenesis in glioblastoma." (PMID 36278207, 2022). "We hypothesized that TSPO plays a critical role in NOX4-mediated extracellular ROS production in glioblastoma." (PMID 36278207, 2022). "Increased NOX4 expression has been observed in glioblastoma tissues." (PMID 35646942, 2022).
glioblastoma (continued). "Two major coordinators of oncogenic metabolic adaptation are the hypoxia inducible factor 1 (HIF-1) and AMP-activated protein kinase (AMPK), and in certain tumor types (e.g., glioblastoma, renal and gastric cell carcinomas) NOX4 has been recognized as a modulator of their signaling." (PMID 35269843, 2022). "Cycling hypoxia drives NOX4 expression to promote resistance to radiotherapy in glioblastoma." (PMID 35646942, 2022). "Moreover, NOX4 protein is expressed in higher levels in glioblastoma stem cells and transition cells compared with glioblastoma differentiated cells." (PMID 35203105, 2022). "In glioblastoma, increased iron level induced by pseudolaric acid B treatment via upregulation of transferrin receptor could upregulate NOX4 expression, thus leading to accumulated lipid peroxides." (PMID 35646942, 2022). "Clinical samples of glioblastoma showed NOX4 expression in Iba1-positive microglia and macrophages." (PMID 36278207, 2022). "In this study, we identify NOX4 as a key player downstream of TGFβ in glioblastoma cells." (PMID 35203105, 2022). "In this study, we identified NOX4 as a key mediator of glioblastoma stem cells (GSC) biology." (PMID 35203105, 2022). "Therefore, we investigated the role of TSPO in subsequent NOX4-derived ROS generation in glioblastoma." (PMID 36278207, 2022). "NOX4 is mainly expressed in endothelial cells of glioblastoma." (PMID 36278207, 2022). "NOX4 also participates in the regulation of TGF-β1-drived metabolic rewiring of glioblastoma cells." (PMID 35646942, 2022). "In addition to drug resistance, we found that NOX4 knockdown increased radiation sensitivity, which is consistent with the study that NOX4 blockage enhances the efficiency of radiotherapy in glioblastoma multiforme xenografts." (PMID 34209278, 2021). "As the effect of adonixanthin on intracellur ROS in glioblastoma cells, it is considered that adonixanthin may inhibit the expression of ROS production-related factors, such as Nox4." (PMID 32962073, 2020). "In addition, the expression of NOX4 is increased at both mRNA and protein levels in hypoxic glioblastoma cells." (PMID 28594389, 2017). "It has also been reported that NOX4-generated ROS are required for promoting hypoxia-induced invasive potential of U87 cells, and that ROS are potential targets for inhibiting tumor cell invasion and infiltration in glioblastoma." (PMID 25915537, 2015). "Inhibition of Nox4 by lentivirus-mediated shRNA could be a strategy to overcome radioresistance and then improve its therapeutic efficacy for glioblastoma." (PMID 24868315, 2014). "Our results indicate that Nox4 may play a crucial role in tumor invasion, angiogenesis, and radioresistance in glioblastoma." (PMID 24868315, 2014). "Therefore, knockdown of Nox4 suppressed both constitutive and radiation-induced angiogenesis in vitro, suggesting an important role of Nox4 derived ROS in angiogenesis process in glioblastoma." (PMID 24868315, 2014). "In the present study, we further confirmed that irradiation induced a marked increase in VEGF protein expression in glioblastoma cells, and Nox4 shRNA could potentially block the radiation-induced enhancement of VEGF." (PMID 24868315, 2014). "Glioblastoma cells and xenografts were compared under cycling hypoxic and normoxic conditions; upregulation of NOX4 expression and ROS levels were observed under cycling hypoxia in glioblastoma cells and xenografts, concomitant with increased tumor cell growth in vitro and in vivo." (PMID 21935366, 2011). "However, Nox4 knockdown or Tempol treatment in glioblastoma xenografts under cycling hypoxic stress inhibited additional cycling hypoxia and endogenous tumor microenvironment-induced ROS production." (PMID 21935366, 2011). "Having linked cycling hypoxia with ROS production, we next sought to determine whether Nox4 knockdown or treatment with an antioxidant compound can suppress cycling hypoxia-induced ROS levels in glioblastoma xenografts." (PMID 21935366, 2011).
glioblastoma (continued). "In glioblastoma multiforme (GBM), NOX4-derived ROS have been shown to promote proliferation and radioresistance." (PMID 39201571, 2024). "We aimed to validate the hypothesis that TSPO regulates angiogenesis via NOX4 in glioblastoma." (PMID 36278207, 2022). "Since our results clearly demonstrated that NOX4 regulates aerobic glycolysis in glioblastoma cells via FOXM1 and that increased glucose metabolism is advantageous for in proliferating cells, we further explored whether FOXM1 is critical for NOX4-regulated cancer proliferation." (PMID 34740322, 2021). "Finally, we investigated the subcellular localization of NOX4 in glioblastoma cells." (PMID 34740322, 2021). "Therefore, and according to this study, NOX4 inhibition with lentivirus shRNA could be an attractive therapeutic option for overcoming radioresistance in glioblastoma." (PMID 33036204, 2020). "Therefore, inhibition of Nox4 by lentivirus-mediated shRNA may be a strategy to overcome radioresistance and then improve its therapeutic efficacy for glioblastoma." (PMID 24868315, 2014). "High levels of NOX4 expression increased the probability of predicting glioblastoma, as evidenced by the positive correlation between the SHAP values for the glioblastoma class and the gene expression values." (PMID 40867242, 2025). "mRNA expression levels of NOX4 in glioblastomas (WHO grade IV) were significantly higher compared to astrocytomas (WHO grades II and III), and OS was significantly lower in patients with high NOX4 expression." (PMID 40867242, 2025). "Pharmacological (PAG) inhibition of CTH on human glioblastoma cells results to lower Glioblastoma Stem Cell (GSC) formation and lower mRNA expression of stem cell markers (i.e, PROM1, NOX4)." (PMID 37300955, 2023). "NOX4 expression levels are increased in GBM compared with lower grade gliomas; their expression is higher in glioblastoma stem cells and transition glioblastoma cells compared with differentiated tumour cells." (PMID 35203105, 2022). "Both TSPO and NOX4 promoted angiogenesis in an ROS-dependent manner, suggesting that TSPO triggered ROS production in glioblastoma via NOX4." (PMID 36278207, 2022). "Using only stem cell markers to classify the cells, we also observed that NOX4 levels were higher in transition and stem GBM cells both in glioblastoma and epithelioid glioblastoma patients, compared with the differentiated GBM cells." (PMID 35203105, 2022). "Because intratumoral hypoxia is a common feature of solid tumors, particularly in glioblastoma, and HIF-1α is downstream of NOX4-derived ROS, we clearly elucidated that NOX4-derived MitoROS induced FOXM1 overexpression by stabilizing HIF-1α." (PMID 34740322, 2021). "Together, these findings reveal that NOX4-derived ROS, especially from mitochondria, are required for an increase in FOXM1 levels in glioblastoma cells." (PMID 34740322, 2021). "As expected, Western blot analysis demonstrated that in glioblastoma cells, overexpression of NOX4 induced HIF-1α protein expression, whereas the opposite was true upon NOX4 knockdown." (PMID 34740322, 2021). "The functions of NOX4 and FOXM1 in aerobic glycolysis in glioblastoma cells were determined by a series of experiments, such as Western blot, extracellular acidification rate (ECAR), lactate production, and intracellular ATP level assays." (PMID 34740322, 2021). "By analyzing samples from the TCGA database and clinical specimens, our data demonstrated that elevated expression of NOX4 and FOXM1 predicted a worse prognosis of glioblastoma." (PMID 34740322, 2021). "NOX4-induced aerobic glycolysis was dependent on elevated FOXM1 expression, as FOXM1 knockdown abolished NOX4-induced aerobic glycolysis in glioblastoma cells both in vitro and in vivo." (PMID 34740322, 2021). "Overexpression of NOX4 or FOXM1 promoted aerobic glycolysis, whereas knockdown of NOX4 or FOXM1 significantly suppressed aerobic glycolysis, in glioblastoma cells." (PMID 34740322, 2021).
glioblastoma (continued). "Among all the different isoforms of NOX, NOX4 has been shown to have the most crucial role in glioblastoma, and NOX4-derived ROS (like H2O2) are essential for glioblastoma invasion and for angiogenesis around the tumor." (PMID 33036204, 2020). "The elevated ROS production by NOX4 plays a vital role for STAT3 activation and angiogenesis in hypoxic glioblastoma cells." (PMID 28594389, 2017). "Transfection of Nox4 shRNA resulted in a significant inhibition of ROS production as compared to scrambled controls, suggesting that Nox4 is one of the major sources of ROS generation in U87MG and U251 glioblastoma cells." (PMID 24868315, 2014). "A lentiviral shRNA vector was utilized to stably knockdown Nox4 in U87MG and U251 glioblastoma cells." (PMID 24868315, 2014). "Nox4 NADPH oxidase is abundantly expressed and has proven to be a major source of ROS production in glioblastoma." (PMID 24868315, 2014). "TGF-β1 is also required for the NOX4-dependent stabilization of HIF1α and of its nuclear accumulation, which results in metabolic reprogramming and in promoting the epithelial mesenchymal transition (EMT) of glioblastoma." (PMID 36768405, 2023). "The results could serve as a basis for exploring therapeutic targets based on the dual inhibition of NOX4 and TSPO in glioblastoma." (PMID 36278207, 2022). "Since NOX4 and FOXM1 regulate aerobic glycolysis in glioblastoma cells, we asked whether NOX4 promotes the Warburg effect by upregulating FOXM1 expression." (PMID 34740322, 2021). "To test this hypothesis, we investigated the roles of NOX4 and FOXM1 and their relationship in glioblastoma cells with in vitro and in vivo experiments." (PMID 34740322, 2021). "To date, whether FOXM1 is regulated by NOX4-derived ROS and the role of FOXM1 expression in glioblastoma aerobic glycolysis remain unknown." (PMID 34740322, 2021). "To analyse the expression of NOX4 in tissues from GBM patients, we performed multiplex immunohistochemistry analysis on two tissue microarrays (TMA) with human GBM, anaplastic astrocytoma, epithelioid glioblastoma, and non‐tumoural brain samples." (PMID 35203105, 2022). "Our previous findings indicated that NOX4 was mainly expressed in endothelial cells of glioblastoma, leading us to determine whether or not NOX4 regulates angiogenesis in glioma." (PMID 36278207, 2022). "Given that higher expression of NOX4 and FOXM1 predicted a worse prognosis in glioma, and based on reports that NOX4 promotes cell glycolysis in a variety of human malignancies, including glioblastoma, we explored the impact of NOX4 and FOXM1 on aerobic glycolysis in glioblastoma cells." (PMID 34740322, 2021). "Increased expression of FOXM1 induced by NOX4-derived MitoROS plays a pivotal role in aerobic glycolysis, and our findings suggest that inhibition of NOX4-FOXM1 signaling may present a potential therapeutic target for glioblastoma treatment." (PMID 34740322, 2021). "We further investigated whether NOX4 and FOXM1 influence glioblastoma proliferation." (PMID 34740322, 2021). "This notion was corroborated in our study because Nox4 silencing significantly reduced the level of VEGF expression of nonirradiated glioblastoma cells and inhibit endothelial cells tube-like structure formation induced by conditioned medium from nonirradiated U87MG cells." (PMID 24868315, 2014). "Additionally, PAG under baseline conditions can significantly reduce the formation of glioblastoma stem cells derived from human GBM cells and downregulate the mRNA expression of genes involved in stem cell formation such as PROM1 and NOX4." (PMID 37300955, 2023).